SYTL1 (synaptotagmin like 1)
Description:
May play a role in vesicle trafficking (By similarity). Binds phosphatidylinositol 3,4,5-trisphosphate. Acts as a RAB27A effector protein and may play a role in cytotoxic granule exocytosis in lymphocytes (By similarity).
Synonyms: SLP1; JFC1; FLJ14996; exophilin-7
Tractability: Antibody: UniProt places it where antibodies can reach, with high confidence; its Gene Ontology location is reachable by antibodies, with high confidence. PROTAC: its protein half-life has been measured.
Gene: Protein-coding gene on chromosome 1 (27,342,009 to 27,353,937, forward strand). Ensembl gene ENSG00000142765.
Subcellular location: Cell membrane
Pathways (Reactome):
Vesicle-mediated transport: TBC/RABGAPs
Gene Ontology:
Molecular function: protein binding; neurexin family protein binding; small GTPase binding
Biological process: exocytosis; intracellular protein transport
Cellular component: extracellular exosome; plasma membrane; exocytic vesicle; melanosome; microvillus membrane
Genetic constraint (gnomAD): Loss-of-function variants: 53 observed, 63.64 expected, observed/expected ratio (o/e) 0.83, 90% interval 0.67 to 1.05. The upper end of that interval is the gene's LOEUF score, 1.05, which puts it in group 4 of 6, group 1 being the genes least tolerant of losing a copy. Missense variants: 728 observed, 690.39 expected, observed/expected ratio (o/e) 1.05, 90% interval 0.99 to 1.12. Synonymous variants: 329 observed, 287.15 expected, observed/expected ratio (o/e) 1.15, 90% interval 1.05 to 1.25.
Homologues: Orthologues: chimpanzee SYTL1 (99% identical), macaque SYTL1 (96% identical), dog SYTL1 (86% identical), pig SYTL1 (86% identical), mouse Sytl1 (82% identical), rat Sytl1 (80% identical), guinea pig SYTL1 (80% identical), rabbit SYTL1 (60% identical), tropical clawed frog sytl1 (43% identical), zebrafish sytl1 (40% identical). Paralogues in human: SYTL2 (43% identical), SYTL4 (33% identical), SYTL5 (31% identical), SYTL3 (28% identical), SYT6 (19% identical), RPH3A (18% identical), SYT3 (18% identical), SYT7 (17% identical), SYT5 (17% identical), SYT9 (17% identical), SYT10 (17% identical), DOC2A (16% identical), and 19 more.
Diseases named in the same sentence as SYTL1 in open-access papers:
SYTL1 is named in the same sentence as 6 diseases in open-access papers, as found by Europe PMC text mining. Sharing a sentence is not in itself a finding about the gene and the disease. The quoted sentences say what the papers report.
lung carcinoma (1 paper, 2023). "Interestingly, Linc01703 does not directly impact the proliferation and invasion capabilities of lung cancer cells but rather inhibits cancer metastasis by promoting the secretion of CD81+ exosomes through the Rab27a/SYTL1/CD81 transport complexes." (PMID 38136327, 2023).
prostate carcinoma (1 paper, 2023). A carcinoma that arises from epithelial cells of the prostate gland. "Previous study indicated that SYTL1 is transcriptionally activated by nuclear factor-κB and up-regulated by tumor necrosis factor αin prostate cancer cell lines." (PMID 36653850, 2023). "In prostate cancer cell lines, SYTL1 is transcriptionally activated by nuclear factor-κB and up-regulated by tumor necrosis factor α." (PMID 36653850, 2023).
tumor (6 papers, 2012 to 2025). "We further assessed the link between SYTL1 and tumor-infiltrating immune cells by using gene set variation analysis (GSVA)." (PMID 36653850, 2023). "Firstly, more experiments need to be carried out to explore the specific function of SYTL1 in tumor microenvironment." (PMID 36653850, 2023). "In UALCAN portal, the differences in SYTL1 phosphorylation levels between primary tumor and normal tissues were analyzed." (PMID 36653850, 2023). "We investigated the genetic alternation status of SYTL1 in different tumor samples according to the cBioPortal database." (PMID 36653850, 2023). "However the role of SYTL1 in tumor progression remains unclear." (PMID 36653850, 2023). "Our data also showed that the VAF of some primary or metastatic-specific SNVs in both tumour lesions was too low to be detected by SNV callers, such as SYTL1 and NPIPB15 in CRC1." (PMID 34507604, 2021). "Thus SYTL1 could play a role as an inhibitor of tumor progression along this pathway." (PMID 22724020, 2012). "Sytl1, a Rab27b partner in hematopoietic cells, facilitates CXCR4 membrane trafficking and promotes occupancy of the bone marrow niche by AML, indicating the importance of the Rab27/Sytl axis in the interaction between tumor cells and the microenvironment." (PMID 37029109, 2023).
cancer (4 papers, 2023 to 2025). A tumor composed of atypical neoplastic, often pleomorphic cells that invade other tissues. "Compared with the adjacent non-cancer tissues, the protein levels of SYTL1 in EC tissues were significantly increased." (PMID 36653850, 2023). "To explore the possible role of SYTL1, we analyzed its expression in 33 types of different cancers." (PMID 36653850, 2023). "These evidences revealed that SYTL1 might be involved in cancer progression." (PMID 36653850, 2023).
SYTL1 also shares sentences with these, for which no sentence is quoted: endometrial cancer (1 paper); lung adenocarcinoma (1).